IL6 (interleukin 6)
Diseases named in the same sentence as IL6 in open-access papers (continued):
Sharing a sentence is not in itself a finding about the gene and the disease.
colitis (continued). "Colitis is seen at 6 weeks age and increased Il-23p19 expression occurred at the start of colitis associated with increased Il-17A, next to Il-1, Il-6, and Tnf-α expression." (PMID 34267743, 2021). "Mlkl-/-mice exhibited massive inflammatory responses and exhibited high IL-6 expression during colitis and colitis-associated tumorigenesis." (PMID 33767595, 2021). "A deeper analysis identified the downregulation of GM-CSF/M-CSF, IL-6, and TNF-α and the inhibition of the NF-κB/IL-6/STAT3 pathway as further contributors to colitis-associated cancer." (PMID 34950252, 2021). "As cytokines of the IL-6 and IL-10 families, including IL-6, IL-10, and IL-22, are implicated in supporting intestinal wound healing and immune regulation during colitis, we evaluated the production of these cytokines upon DSS treatment." (PMID 33673239, 2021). "It suppresses colitis symptoms by inhibiting the IL-6/STAT3 signaling pathway in IL-10 deficient mice as well as in an in vitro culture of colonic explants of patients with CD." (PMID 34068714, 2021). "For example, GNAI1 and GNAI3 were found to reduce colitis-associated tumorigenesis in mice through blocking of IL6 signaling and down-regulation of the expression of GNAI2." (PMID 34992636, 2021). "The FMTs from patients with IBD/D+ or IBD/D− all caused colitis in mice: they significantly induced colon shortening; upregulated myeloperoxidase activity, IL-1β and IL-6 expression and increased the NF-κB+/CD11c+ cell population in the colon." (PMID 34650107, 2021). "Taken into account, TNF-α and IL-6 play an important role in body-weight loss induced by the secretion of neuropeptides, suppressing the appetite in colitis." (PMID 35052720, 2021). "We used dextran sulfate sodium (DSS) to induce colitis and found that ginger alleviated colitis-associated pathological changes and decreased the mRNA expression levels of interleukin-6 and inducible nitric oxide synthase in mice." (PMID 33692694, 2021). "FMTs from patients with IBD/D+ or IBD/D− caused IBD-like colitis in the transplanted mice: they increased the myeloperoxidase activity, IL-1β and IL-6 expression, and NF-κB+/CD11c+ cell population in the colon." (PMID 34650107, 2021). "Shaoyao decoction decreases the expression of TNF-α, IL-1β, and IL-6 in DSS-induced colitis-associated CRC." (PMID 32565784, 2020). "In TPH1 deficient colitis mice, the severity of colitis and the level of IL-1β, IL-6, and tumor necrosis factor (TNF)-α was clearly reduced, and reloading 5-HT increased the severity of DSS-induced colitis." (PMID 32117308, 2020). "IL-1β is known to stimulate diarrhea, immune cell infiltration, and intestinal necrosis, and IL-6 reduction had shown to slow down the development of UC and colitis-associated colon cancer." (PMID 33041812, 2020). "Recent evidence demonstrates that “trans” IL-6 signaling, involving extracellular binding of IL-6 and its soluble receptor is more important for the osteoclastogenic response to IL-6 in rheumatoid arthritis, estrogen deficiency, and colitis." (PMID 33834150, 2020). "Several studies have shown the Treg involvement in colorectal tumorigenesis, e.g. IL-6 and IL-10 both enhanced tumorigenesis in colitis-associated cancer models, whereas blockade of IL17A inhibited tumor growth." (PMID 32677955, 2020). "Nrf2-deficient mice were susceptible to DSS-induced colitis, because of the reduced levels of antioxidative enzymes, including HO-1, along with the elevated levels of the pro-inflammatory mediators, including IL-6, TNF-α, iNOS and COX-2." (PMID 32290483, 2020). "Macrophages are the main producers of IL-6 and are therefore mediators of IL-6 driven inflammation and tumour promotion in colitis associated cancer." (PMID 32883606, 2020). "Exosomes from M2b macrophages were found to significantly reduce the severity of dextran sulfate sodium (DDS)-induced colitis in mice and inhibit the expression of key cytokines associated with colitis (IL-1, IL-6, and IL-17A)." (PMID 32411539, 2020).
colitis (continued). "In fact, neutrophil recruitment is closely related to UC, and it can promote the development of colitis-associated tumorigenesis by activating the IL-1/IL-6 axis, and participate in the epithelial homeostasis of the colonic epithelial barrier in UC." (PMID 32982747, 2020). "Our results indicated that AphaMax® treatment caused a dose-dependent reduction of both IL-6 and IL- 1β cytokine levels in colitis rats, thus ameliorating the deregulated immune response typical of experimental colitis." (PMID 33256017, 2020). "Lower baseline levels of IL-6, IL-8, and sCD25 were associated with subsequent colitis in metastatic melanoma patients treated with ipilimumab." (PMID 33123120, 2020). "Conversely, the genetic loss of IL-6 or the antibody blockade of IL-6 results in attenuated colitis following intestinal inflammation." (PMID 30818341, 2019). "Dizocilpine, particularly with intermediate dose of 1mg/kg significantly improved animal’s weight loss as well as macroscopic and microscopic signs of colitis, reduced colonic levels of IL-1β, IL-6, TNF-α and MPO activity." (PMID 32641944, 2019). "Exposure to IS alone significantly caused colitis: It induced colon shortening, colonic myeloperoxidase activity, proinflammatory cytokine IL-6 and IL-1β expression, and NF-κB activation, and COX-2 expression." (PMID 30979031, 2019). "In the case of CRP, IL-6, IL-12, and IL-10, the addition of both beta-glucans to the feed of animals with induced colitis caused a statistically significant reduction of their level to the level observed in healthy control group (HβG−) or even lower." (PMID 31590413, 2019). "IL-17 has been shown to both induce the proliferation of transformed enterocytes and stimulate IL-6 production, a cytokine implicated in colitis-associated carcinogenesis." (PMID 29922293, 2018). "In a recent study, adiponectin-deficient mice treated with DSS exhibited more severe colitis accompanied by an increased presence of activated B cells, pro-inflammatory cytokines such as IL-1β, IL-4, and IL-6 and increased STAT3 signaling in the colon." (PMID 30369924, 2018). "Taken together, our study demonstrated that silibinin administration ameliorated colitis and inhibited colitis-associated tumorigenesis via inhibition of IL-6/STAT3 signaling pathway." (PMID 30498394, 2018). "IL-6 has been shown to play a critical role in the development and progression of colitis and colitis-associated cancer." (PMID 30042683, 2018). "IL-17RA signaling also induced IL-6 expression, a cytokine previously associated with colitis-associated cancer development." (PMID 29922293, 2018). "TNF-α and IL-6 signaling has been proposed as a tumor-promoting mechanism in colitis-associated cancer." (PMID 29636751, 2018). "Concomitantly, expression of Il6, Tnf and Il1β were reduced in colitis colons of CCR-6-deficient mice." (PMID 29695802, 2018). "Body weight loss in colitis and colitis-induced expression of Il6, Tnf, Il1β and Il10 were reduced in JHT mice." (PMID 29695802, 2018). "We observed increased IL-1β and IL-6 expressions in Rev-erbα-deficient mice at early stage of colitis (2 days of DSS feeding)." (PMID 30315268, 2018). "Recent studies have demonstrated that the IL-6/STAT3 pathway is a crucial tumor promoter in colitis-associated cancer." (PMID 28852270, 2017). "A protective role of VitK was shown in a model of DSS-induced colitis associated with a reduction in IL-6 production from B cells." (PMID 28804483, 2017). "It was later shown that NOD2 deficiency increases the susceptibility of mice to chemically induced colitis and colitis-associated carcinogenesis, and this is due to changes in the composition of gut bacterial communities and enhanced IL-6 production." (PMID 28632155, 2017). "In inflammation induced mouse models of CRC it was shown that IL-17A deficient mice showed milder colitis, fewer and smaller tumors and expressed reduced levels of IL-6 and TNF." (PMID 28881611, 2017).
colitis (continued). "TNF-α and IL-6 are both central proinflammatory cytokines associated with the development of intestinal inflammation in animal colitis models and human IBD." (PMID 28607633, 2017). "The loss of Adamdec1 rendered mice more susceptible to the induction of bacterial and chemical induced colitis, as evidenced by increased neutrophil infiltration, greater IL-6 and IL-1β secretion, more weight loss and increased mortality." (PMID 27226416, 2016). "Galectin-4 was demonstrated to exacerbate intestinal inflammation by directly stimulating the CD4+ T cells to produce IL-6 on TCR mutational colitis model." (PMID 27017379, 2016). "Our previous study reported that oroxylin A, a natural flavonoid, inhibited colitis-associated carcinogenesis through modulating IL-6/STAT3 pathway in AOM/DSS mouse model and in HCT116 cells." (PMID 27057094, 2016). "TNF-α, IL-1, and IL-6 have been demonstrated to promote colorectal and colitis-associated tumor development." (PMID 27388564, 2016). "We found that the mice deficient for both IL-6 and IL-15 (IL-15koIL-6koRAG2ko) were resistant to T-cell-induced colitis in contrast to IL-15koRAG2ko mice." (PMID 26964669, 2016). "This was related to CAC by the observation that STAT3 hyperactivation in IECs not only led to decreased susceptibility for colitis but also to increased occurrence and growth of tumors through IL-6 and IL-11." (PMID 26938566, 2016). "This is in good agreement with data showing that Dmbt1−/− mice were more susceptible to colitis and showed elevated mRNA levels for IL-6 and TNF during inflammation." (PMID 25885541, 2015). "Mechanistically, resistance to colitis was associated with suppression of colonic NF-κB signaling and IL-6 synthesis, along with diminished neutrophil and macrophage production and recruitment in Iqgap2-/- mice." (PMID 26047140, 2015). "Inhibition of the IL-6 signaling pathway inhibits tumor development in a colitis-associated carcinogenesis model." (PMID 24885636, 2014). "In agreement with a previous report using Il-6r-deficient mice, our results demonstrated that neutralizing IL-6 mAbs slightly improved DSS-induced colitis." (PMID 24993179, 2014). "In vivo treatment with AL-PS was shown to reduce dextran sodium sulphate (DSS)-induced weight loss, clinical signs of colitis and secretion of interleukin (IL)-6 (p < 0.05)." (PMID 25501329, 2014). "In acute situations, such as chemically induced colitis, IL-6-deficient mice had higher levels of inflammation than wild type mice." (PMID 25110521, 2014). "In the present study, we compared Il-6r-deficient mice with mice treated with neutralizing IL-6 monoclonal antibody (mAb) in a model of dextran sodium sulfate (DSS)-induced colitis." (PMID 24993179, 2014). "In dextran sodium sulfate induced colitis and the associated model of colitis-induced cancer, CD11b+ lamina propria mononuclear cells were the source for IL-6 that drove tumorigenesis several weeks after initiation of the disease model." (PMID 25478789, 2014). "LJE alone caused a significant improvement of colitis signs such as colon length, histological score, and IL-1β and IL-6 production." (PMID 24948848, 2014). "While we demonstrated a correction of the epithelial proliferation defect, mice treated with the inhibitory IL-6 antibody three days after induction of colitis still developed disease with increased crypt loss compared to control antibody treated dnKO mice." (PMID 25478789, 2014). "(iv) DSS-induced colitis was associated with an increase in circulating IL6, IL18, and NPY, an increased expression of COX-2 mRNA in the hypothalamus, and a decreased expression of BDNF, NPY, and MR mRNA in the hippocampus." (PMID 25414650, 2014). "The leukocyte infiltration into the mucosa and submucosa of the small intestine of mice with colitis at 6 DPI was associated with increased concentration of IL-6, IL-12p70, IL-10, IL-22 MCP-1 and TNF-α, IL-1β, MPO but lower concentration of IL-17A." (PMID 24167594, 2013).
colitis (continued). "IL-23p19, IL-17, and IRF4 deficient mice were both protected from colitis-related symptoms, including weight loss and production of high levels of proinflammatory cytokines including IL-6, IL-17, and IL-22." (PMID 24454481, 2013). "In this model, IL-21-deficient mice developed a less severe colitis than wild-type mice, characterized by reduced mucosal damage, reduced infiltration of T cells, and diminished production of IL-6 and IL-17A." (PMID 23109839, 2012). "Our results provide supporting evidence for the crucial role of IL-6 in the generation of colonic inflammation, as IL-6 blockade delayed disease onset and attenuated colitis-associated symptoms in DSS-treated mice." (PMID 22962574, 2012). "An essential role of IL-6 trans-signaling in the development of colitis-associated CRC is also reported by Matsumoto and colleagues." (PMID 23109839, 2012). "With regard to this possibility, administration of IL-6R mAb to SCID mice, after transfer of CD45RBhigh T cells, confers protection from colitis, and IL-6–deficient mice have been shown to be less susceptible to colitis." (PMID 21966415, 2011). "Most recently, IL-6 has been reported as a critical tumor promoter during early colitis-associated tumorigenesis." (PMID 19907660, 2009). "In contrast, hFcgR mice given IgG from patients with colitis developed colon inflammation marked by a significant increase in submucosal lymphocyte infiltration, goblet cell loss, and circulating cytokines, including IL-6, IL-17, and IL-22." (PMID 42282671, 2026). "In TAMs, canonical NF-κB (RelA/p50) promotes proinflammatory cytokine production (e.g., TNF-α, IL-6) in inflammation-driven cancers (e.g., colitis-associated colon cancer) or immunosuppressive IL-10 secretion in breast and ovarian cancers, fostering tumor growth and immune escape." (PMID 40562870, 2025). "In contrast, poor outcomes and increased risk of irAE recurrence have been associated with high-grade CIP, initial irAE of colitis or hepatitis, advanced age, and elevated levels of IL-6, CRP, WBC, and absolute neutrophil count (ANC) at the time of rechallenge." (PMID 40984918, 2025). "The findings indicated that curcumin effectively mitigated weight loss and colon shortening caused by colitis, enhanced the expression of anti-inflammatory factor IL-10 mRNA (p < 0.05), and suppressed the expression of pro-inflammatory factors (IL-1β, IL-6, and TNF-α mRNA; p < 0.05)." (PMID 40724653, 2025). "Notably, in the mouse mastitis model, mastitis was associated with colitis and systemic inflammatory response, as evidenced by elevated IL‐6, TNFα, and IL‐1β levels in circulation and colonic tissues (P < 0.01)." (PMID 40552401, 2025). "Pre-clinical studies have also implicated IL-6 in impaired immune responses, arthritis, colitis, and multiple sclerosis and activation of mucosal T cells induced by IL-6-sIL-6R exacerbates Crohn disease, a chronic inflammatory disease of the gastrointestinal tract chronic intestinal inflammation." (PMID 40114923, 2025). "Using a mouse model of HFD + trinitrobenzene sulfonic acid (TNBS)-induced colitis, dietary n-3 PUFAs have been shown to reduce colitis-associated disease severity and colonic mRNA expression of cytokines (IL-6, IL-17A, IL-17F, IL-21, IL-23, and IFNγ) versus corn oil in control HFD mice." (PMID 40219010, 2025). "Moreover, Rhbdd3 has been reported as a suppressor of the production of IL-6 by inhibiting K63-linked polyubiquitination of NEMO in dendritic cells to control Th17 cell-mediated colitis caused by excessive activation of dendritic cells." (PMID 38346956, 2024). "Therefore, it is important to suppress the hyperactivation of the intestinal IL-6 signaling pathway caused by colitis and regulate it to steady-state levels." (PMID 38916850, 2024). "Colitis causes there to be an inflammatory environment leading to IL-6 release." (PMID 39839775, 2024).
colitis (continued). "Additionally, researchers have reported that neutrophils can secrete IL-1 and promote colitis-associated tumorigenesis by activating the IL-1/IL-6 axis." (PMID 39717480, 2024). "Given the profound association of IL-6 with Th17 cells, recognized as significant contributors to inflammation in colitis or IBD, recent endeavors have sought to incorporate IL-6 blockade alongside dual PD-1 and CTLA-4 blockade to mitigate the irAE and enhance tumor immunity." (PMID 38785789, 2024). "Our results showed that induction of colitis caused bloody diarrhea and increased IL-6 levels." (PMID 39134818, 2024). "Neo treatment exerted the best effect in attenuating DSS-induced colitis, manifested by the least body weight loss, longer colon as well as lower colonic mRNA levels of proinflammatory cytokines and IL-6 protein." (PMID 38351003, 2024). "Conversely, Arhgef2 deficiency causes susceptibility to colitis, expressed as increased pathology score, increased production of inflammatory cytokines (IL6, MCP1, RANTES, C4b), increased infiltration of CD45+ cells in the lamina propria, with a marked abundance of CD11b+/Ly6G+ neutrophils." (PMID 38200184, 2024). "Earlier reports also revealed that blocking TNF-α, IL-1β, or IL-6 caused an anti-colitis effect." (PMID 37509556, 2023). "Deletion of IL-6 exacerbates colitis and induces systemic inflammation in IL-10-deficient mice." (PMID 38137450, 2023). "Colitis-associated myeloid cells have higher expression of genes involved in innate inflammatory pathways, suggesting that pathology is driven by inflammasome activation and production of IL-1β, IL-6, and TNFα." (PMID 37461742, 2023). "Importantly, intravenous injection with T-MSCs protected mice from colitis-related tissue damage, manifested as reduced loss of body weight and colon length and reduction of IL-6 in serum." (PMID 37723551, 2023). "In addition, berberine is another antioxidant that inhibits the development of colitis-associated colorectal cancer by interfering with TNFα and IL-6-induced inflammatory responses in colonic macrophages, thereby inhibiting EGFR/ERK signaling in tumor cells." (PMID 36670988, 2023). "Thus, during acute DSS-induced colitis in mice, H4R activity caused the increased expression of IL-5, IL-6, IL-10, IL-17, and IFN-γ after restimulation by αCD3 antibodies in lymph node cells compared to the control." (PMID 37373085, 2023). "First, the IL-6/STAT3 pathway is a key signaling pathway in colitis-associated colorectal cancer." (PMID 37251321, 2023). "In a colitis-associated colon cancer mouse model, L. bulgaricus decreased intestinal inflammation and reduced tumour levels of IL-1β, IL-6, IL-17, IL-23 and TNF-α; L. acidophilus, L. rhamnosus and B. bifidum also reduced TNF-α and increased IL-10 in the colon of this mouse type." (PMID 35408849, 2022). "In addition, the IL‐6 downstream STAT3 signalling pathways are persistently activated during colitis‐associated carcinogenesis." (PMID 35363937, 2022). "Indeed, it has been shown in a TCR mutational colitis mouse model that galectin-4 can trigger IL-6 expression/secretion from activated CD4+ T cells." (PMID 36139125, 2022). "(50, 100, 200 mg/kg) could protect against the TNBS-caused colitis in a rat model by decreasing the levels of IL-33, IL-5, IL-13, IL-6 cytokines and expression of IL-33 and ST2 proteins to inhibit the IL-33/ST2 signaling pathway." (PMID 36160392, 2022). "Pg implantation in the rectum induced overexpression of TNF-α and IL-6, followed by loss of surface epithelium, destruction of crypts, and infiltration of inflammatory cells, thereby exacerbating the clinical symptoms of colitis in this mouse model." (PMID 35056032, 2022). "For example, the application of a commonly utilized NSAID, aspirin, in a mouse model of colitis-linked colon cancer, led to a decrease in the active histone H3K27ac levels and accompanying repression of the proinflammatory genes TNFα, IL-6 and inducible nitric oxide synthase (iNOS)." (PMID 35757000, 2022).